ALX4 (ALX homeobox 4)
Diseases named in the same sentence as ALX4 in open-access papers (continued):
Sharing a sentence is not in itself a finding about the gene and the disease.
lung carcinoma (4 papers, 2015 to 2020). "It has been shown in lung cancer and colorectal neoplasia that ALX4 is epigenetically silenced via hypermethylation." (PMID 32539762, 2020). "Our previous study on lung cancer has identified numbers of CpG islands on the ALX4 promoter region and epigenetically silencing by promoter hyper-methylation have been reported to be a major reason for gene down regulation." (PMID 29183346, 2017). "We have previously showed that ALX4 suppressed lung cancer proliferation by activating the caspase cascade and a recent study showed that ALX4 suppressed the EMT of liver cancer by inhibiting the sonic hedgehog (Shh) pathway." (PMID 29183346, 2017). "In lung cancer, ALX4 expression was silenced by hypermethylation, and ectopic expression of ALX4 suppressed proliferation of lung cancer cells in vitro and in vivo." (PMID 25944620, 2015). "We have previously reported that ALX4 could suppress lung cancer progression by inducing cell apoptosis." (PMID 29183346, 2017). "In lung cancer, the ALX4 expression was silenced by hypermethylation, and ectopic expression of this protein could inhibit proliferation of lung cancer cells in vitro and in vivo." (PMID 27895854, 2016).
omphalocele (4 papers, 2011 to 2022). Omphalocele is an embryopathy classified in the group of abdominal celosomias and is characterized by a large hernia of the abdominal wall, centered on the umbilical cord, in which the protruding viscera are protected by a sac. "This is similar to the situation with the Alx4 mutant mouse, which was originally described to exhibit gastroschisis but was later reported to exhibit exomphalos." (PMID 24094954, 2013). "We analyzed the lower body wall phenotypes of combinatorial mutantsof Shh, Gli3 and Alx4 genes.We also analyzed conditional gain-of-function mutants of Hh signaling andrevealed the Hh signal dose-dependent pathogenesis of omphalocele and pubicdiastasis phenotypes." (PMID 21283718, 2011). "Moreover, mouse mutants of Sonic hedgehog (Shh), GLI-Kruppel family member 3 (Gli3) and Aristaless-like homeobox 4 (Alx4), members of the hedgehog signaling pathway, were involved in ventral body wall malformation especially in pups with omphalocele phenotypes." (PMID 35885957, 2022).
ovarian carcinoma (4 papers, 2015 to 2025). A malignant neoplasm originating from the surface ovarian epithelium. "According to TCGA and GEO data, ALX4 is also amongst the most differentially methylated genes in ovarian cancer, and its hypermethylation is associated with chemoresistance." (PMID 40002854, 2025). "Recent studies showed its opposing roles in HCC and ovarian cancers via distinct mechanisms indicating the functions and regulation mechanisms of ALX4 in the progression of different tumor remain largely uninvestigated." (PMID 29183346, 2017). "In this report, we show that two homeoproteins, HOXB13 and ALX4, can induce the expression of the EMT-associated transcriptional factor SLUG and promote invasion and EMT of ovarian cancer cells." (PMID 25944620, 2015). "Promotion of EMT by either HOXB13 or ALX4 expression was also observed in another ovarian cancer cell line, NOS3." (PMID 25944620, 2015). "In summary, we have shown that two homeoproteins, HOXB13 and ALX4, are associated with EMT and invasion of ovarian cancer cells." (PMID 25944620, 2015). "In this study, we show that two homeoproteins, HOXB13 and ALX4, are associated with epithelial to mesenchymal transition (EMT) and invasion of ovarian cancer cells." (PMID 25944620, 2015). "We examined level of ALX4 mRNA in ovarian cancer cell lines." (PMID 25944620, 2015). "ALX4, another tumor suppressor in the HOX family is involved in the promotion of ovarian cancer metastasis: ALX4, together with the other HOX protein HOXB13 promotes epithelial to mesenchymal transition factor SLUG in ovarian cancer cell lines." (PMID 40002854, 2025). "We showed that ALX4 had tumor-promoting function by promoting EMT and invasion in ovarian cancer cells." (PMID 25944620, 2015). "Our results show that HOXB13/SLUG and ALX4/SLUG axes are novel pathways that promote EMT and invasion of ovarian cancer cells." (PMID 25944620, 2015).
Potocki-Shaffer syndrome (4 papers, 2011 to 2022). Potocki-Shaffer syndrome is characterized by multiple exostoses, parietal foramina, enlargement of the anterior fontanelle and occasionally intellectual deficit and mild cranio-facial anomalies. "In Gollop-Wolfgang complex and Langer-Giedion syndrome, deletions on chromosome 8q have been identified, whereas Potocki-Shaffer syndrome is caused by deletion and/or mutations of the ALX4 gene on chromosome 11p11.2." (PMID 26076463, 2015). "Data from literature relates PHF21A variants with Potocki-Shaffer Syndrome (PSS), a contiguous gene deletion disorder caused by the haploinsufficiency of PHF21A, ALX4, and EXT2 genes." (PMID 36555772, 2022). "The Potocki-Shaffer syndrome (P11pDs or DEFECT11 syndrome) (OMIM 601224) is caused by deletions in 11p11.2-p12, including the EXT2 and ALX4 genes, and is characterized by patients having MO combined with Foramina Parietalia Permagna (FPP) (OMIM 168500), mental retardation and craniofacial dysotosis." (PMID 21703028, 2011).
alopecia (3 papers, 2011 to 2017). Hair loss usually from the scalp. "In human, ALX4 loss-of-function mutations underlie autosomal recessive frontonasal dysplasia 2 syndrome, characterized by skull defects, wide nasal bridge, notched nares, depressed nasal tip, hypertelorism and alopecia (OMIM 613451)." (PMID 29028795, 2017).
adenoma (2 papers, 2020 to 2021). A neoplasm arising from the epithelium. "Although methylated markers such as RASSF1A, SDC2, BCAT1, IKZF1, ALX4, SDC2 and WIF-1, among others, have demonstrated some usefulness for the detection of established cancers, the goal of detecting precancerous adenomas has not been achieved yet." (PMID 32605302, 2020).
bladder cancer (2 papers, 2021 to 2023). "ALX4 was methylated in 25% of the urine sediments of bladder cancer patients, whereas no methylation of ALX4 was observed in non-malignant urinary lesions." (PMID 37627900, 2023).
colorectal adenoma (2 papers, 2010 to 2016). An adenoma that arises from the colon or rectum. "Similar to our previous reports on ALX4 and SEPT9 methylation in CRC patients, we found a high frequency of DNA methylation in plasma of patients with colorectal adenomas." (PMID 20140221, 2010).
medulloblastoma (2 papers, 2015 to 2016). A malignant, invasive embryonal neoplasm arising from the cerebellum. "In contrast, ALX4 was remarkably expressed in a subtype of medulloblastoma, as the most common pediatric brain tumor." (PMID 27895854, 2016). "By contrast, ALX4 was strongly expressed in a subtype of medulloblastoma, which is the most common pediatric brain tumor." (PMID 25944620, 2015).
aniridia (1 paper, 2022). Aniridia is a congenital ocular malformation characterized by the complete or partial absence of the iris. "MPPED2, ALX4, and EXT2 are associated with WAGR syndrome (Wilms’ tumor, aniridia, genitourinary anomalies, and mental retardation), a developmental disorder." (PMID 36292693, 2022).
brain malformations (1 paper, 2020). "This case report describes the genetic basis for recognized subtypes of PFM and the rare association of brain malformations associated with PFM due to mutations in the ALX4 homeobox gene." (PMID 33269135, 2020).
ciliopathy (1 paper, 2022). A genetic disorder of the cellular cilia or the cilia anchoring structures, the basal bodies, or of ciliary function. "The targets of CREBP1 found from among the genes shared between the HLHS and ciliopathy interactomes were EP300, PRNP, SMAD3, SUMO1 and TBX6, while the targets of ALX4 were JUN and TCF7L2." (PMID 35456433, 2022).
Cognitive impairment (1 paper, 2021). Abnormal cognition is characterized by deficits in thinking, reasoning, or remembering. "Alx4 has recently been found to be associated with cognitive impairment, congenital disorders of the brain, and normal function of the nervous system." (PMID 34337051, 2021).
colorectal tumors (1 paper, 2013). "Finally, we performed methylation-specific PCR on 76 colorectal tumors to determine DNA methylation status for CSMD1 and known methylation targets ALX4, RUNX3, NEUROG1, and CDKN2A." (PMID 23505554, 2013).
cone-rod dystrophy (1 paper, 2025). Inherited retinal dystrophies that belong to the group of pigmentary retinopathies. "In contrast, a CRX E42A variant associated with cone rod dystrophy was found to disrupt cooperativity and behaved similarly as the PHOX2B E42Q and ALX4 E42A variants." (PMID 41279221, 2025).
frontofacionasal dysplasia (1 paper, 2011). Fronto-facio-nasal dysostosis is characterized by multiple craniofacial anomalies (brachycephaly, blepharophimosis, ptosis, S-shaped palpebral fissures, coloboma, cleft lip and palate, deformed nostrils, encephalocele, hypertelorism, midface hypoplasia, malformed eyes, and absent inner eyelashes). "The clinical symptoms caused by the loss-of-function mutations of the ALX1 gene were related to the clinical spectrum of frontofacionasal dysplasia caused by the two other ALX genes, ALX3 and ALX4." (PMID 21595979, 2011).
frontonasal dysplasia 2 (1 paper, 2021). "ALX4 mutations result in functional haploinsufficiency, such as the development of frontonasal dysplasia 2, impaired interfollicular epidermal differentiation and perturbed regular hair follicle differentiation." (PMID 33836758, 2021).
gastric adenocarcinoma (1 paper, 2016). "The objective of this experiment was to evaluate the ALX-4 mRNA expression level in different stages of human gastric adenocarcinoma compared to the gastric cancer stem cells (GCSC) and gastric cancer cell line, MKN-45." (PMID 27895854, 2016).
gastric cancer (1 paper, 2016). A primary or metastatic malignant neoplasm involving the stomach. "The mRNA expression of ALX-4 associated with gastric cancer invasion and resistance to target therapy." (PMID 27895854, 2016). "In addition, we determined that ALX-4 mRNA expression level was associated with the clinical characteristics (such as grade, stage) in gastric cancer tissues." (PMID 27895854, 2016). "Although, these data proposed that ALX-4 expression in gastric cancer tissues has a higher degree of tumor complexity." (PMID 27895854, 2016). "Curiously, the mRNA expression level of this gene was determined to be higher in early stages of malignancy, suggesting the crucial role of ALX-4 protein in prognosis of gastric cancer." (PMID 27895854, 2016). "In this study, we determined that ALX-4 is significantly up-regulated in most of the gastric cancer cases." (PMID 27895854, 2016). "In this study, we evaluated ALX-4 mRNA expression levels in 37 samples of gastric cancer tissue with different development grads, in comparison with respective normal gastric tissue, derived from the tumor peripheral normal regions." (PMID 27895854, 2016). "Findings showed that 45.94% of gastric cancer patients highly expressed ALX-4(>3.5 fold), 43.24% expressed moderately (1.5-3.5 fold), and 10.81% of the patients showed low expression of this mRNA gene (<1.5 fold), compared to the control group." (PMID 27895854, 2016). "Overexpression of ALX-4 was detected in 46% (3.351±2.94, P<0.05) of gastric cancer tissue specimens and GCSCs (4.31±0.04, P<0.005)." (PMID 27895854, 2016). "In the present study, our findings showed that ALX-4 mRNA level in gastric cancer patients were significantly higher compared to the control group." (PMID 27895854, 2016). "In this study, we evaluated the mRNA expression level of the ALX-4 in gastric cancer tissues, gastric cancer stem cell and MKN-45 cell line." (PMID 27895854, 2016). "In addition, we investigated the interrelationship of the ALX-4 mRNA expression level and malignancy stage, grade, tumor recurrence and metastasis, as well as overall survival rate in Iranian gastric cancer patients." (PMID 27895854, 2016). "Regarding over-expression of ALX-4 in gastric cancer stem cells and malignant gastric tissues, this gene may play a critical role in the maintenance of the tumor phenotype." (PMID 27895854, 2016). "Here, we reported that high level of ALX-4 mRNA and protein expressions could potentially be a novel biological marker correlating with early stages of the gastric cancer development." (PMID 27895854, 2016). "The mRNA expression level of ALX-4 in MKN-45 gastric cancer cell line was 2.81±0.07 (P<0.005)." (PMID 27895854, 2016). "However, our results suggested that there might be some relationship between ALX-4 expression and early grade or stage of gastric cancer development, raising the potential prognostic capacity of this protein to diagnose early stage/grade gastric tumors." (PMID 27895854, 2016). "In addition, ALX-4 gene expression was investigated in gastric malignant cell lines (MKN-5), as well as gastric cancer stem cells (GCSCs)." (PMID 27895854, 2016).
glioblastoma (1 paper, 2025). The most malignant astrocytic tumor (WHO grade IV). "Many of the identified differentially expressed genes are understudied in glioblastoma; however, several are key regulators of tissue remodeling (MFAP4 and ALX4), mesoderm development (TBX5 and ALX4), and immune modulation (FUT2, C4BPA, MFAP4, and GRM4)." (PMID 41066027, 2025).
microphthalmia (1 paper, 2022). Congenital or developmental anomaly in which the eyeballs are abnormally small. "Disruption of ALX1 causes severe facial clefting and microphthalmia in FND3 patients, whereas loss of function mutations in ALX3 and ALX4 underlie the milder FND1 and FND2 syndromes, respectively." (PMID 35127681, 2022).
neuroblastoma (1 paper, 2025). Neuroblastoma (NB) is the most common solid, extracranial childhood tumor. "For example, ALX4 was found to bind the P3 site in human cranial neural crest cells; Phox2a enriched for P3 dimer sites in cortical motor neurons; and PHOX2B predominantly binds to only P3 sites in KELLY, BE2C, and CLBGA neuroblastoma cell lines." (PMID 41279221, 2025).
pancreatic cancer (1 paper, 2016). "Cell-free DNA hypermethylation of BMP3, MESTv2, SST, TFPI2, TAC1, ALX4, HIC1, SFRP2, SEPT9v2 and WNT5A has not previously been described in the literature in relation to pancreatic cancer." (PMID 27891190, 2016).
polyp (1 paper, 2010). A usually exophytic mass attached to the underlying tissue by a broad base or a thin stalk. "In the high sensitivity determination, ALX4 methylation was detectable in 13 of the 22 healthy controls (59%), 38 of the 49 polyp patients (78%) and in 4 of 5 (80%) cancer patients." (PMID 20140221, 2010).
thyroid cancer (1 paper, 2019). "LINC00313 is highly expressed in thyroid cancer and negatively regulates aristaless-like homeobox 4 (ALX4) expression." (PMID 31717266, 2019).
cancer (15 papers, 2010 to 2025). A tumor composed of atypical neoplastic, often pleomorphic cells that invade other tissues. "Among the identified markers, ALX4 demonstrated progressively increased signal with cancer stage and exhibited robust support from cohort analyses." (PMID 41258415, 2025). "ALX4 is a recognized tumor suppressor that functions in the Wnt/β-catenin signaling pathway and is often silenced through hypermethylation in various cancers." (PMID 39649173, 2024). "Then, 37 fresh gastric tissue samples from cancer patient were subjected for expression analysis by quantitative RT-PCR, prior to any therapeutic intervention in the comparative study for evaluation of ALX-4 gene expression." (PMID 27895854, 2016). "In addition to the critical function of ALX4 in development, recent studies have reported the relation of ALX4 expression with cancer." (PMID 27895854, 2016). "In addition to the critical function of ALX4 in development, recent studies have reported the correlation of ALX4 expression with cancer." (PMID 25944620, 2015). "Moreover, in SMC-like cells (14D), we also observed the expression of pro-apoptotic genes, such as Alx4 and Npas2, which are frequently reported in cancer research, suggesting they may have an adverse impact on adipose tissue browning." (PMID 40118146, 2025). "Moreover, ALX4, PDLIM1, CAP2 and EDIL3 have also been found to be correlated with the prognosis of cancer." (PMID 28178989, 2017).
tumor (15 papers, 2014 to 2025). "This is compatible to the previous reports, which implicated the preservative role of ALX-4 in tumor phenotype, suggesting an oncogenic effect for this protein." (PMID 27895854, 2016). "In summary, the combined detection of SEPT9, SDC2, and ALX4 methylation status in plasma can cover multiple molecular pathways of tumor formation and further improvement in detection sensitivity, especially of the PL." (PMID 37881109, 2023). "We found that overexpression of ALX4 significantly inhibited the growth of tumors formed by BT-474 in vivo in terms of both tumor volume and weight, supporting our conclusion that ALX4 is tumor-suppressive." (PMID 32539762, 2020). "Mechanism study found that ALX4 exerted its anti-tumor function by suppressing the Wnt/β-catenin pathway through promoting the phosphorylation degradation of β-catenin in a GSK3β dependent manner." (PMID 29183346, 2017). "Luciferase reporter assay, western blot and TCGA database were used to investigate the tumor suppression mechanisms of ALX4." (PMID 29183346, 2017). "Next, we sought to determine the impact of ALX4 expression on patient survival considering tumor size, clinical stage, lymph node and histological grade." (PMID 29183346, 2017). "Wif-1 appeared to be the most sensitive marker of advanced neoplasia in either urine or serum samples (52% and 29%) compared to ALX-4 and Vimentin (23% and 15% vs. 4% and 8%, respectively)." (PMID 25025467, 2014). "Notably, ALX4 functions as a tumor suppressor whose silencing by promoter hypermethylation contributes to tumorigenesis." (PMID 41258415, 2025). "Similarly, these results showed that the ALX-4 mRNA expression level was reduced with developing tumor grades." (PMID 27895854, 2016). "Promoter methylation of at least one HOX related gene (ALX4, CDX2 or HOPX) or ARID1A gene was detected in 83.08% (54/65) of tumor samples." (PMID 40002854, 2025). "We further consolidated our observation by detecting the expression of ALX4, β-catenin, p-β-catenin and GSK-3β in xenograft tumor tissues by WB." (PMID 29183346, 2017). "Notably, several homeodomain transcription factors were overexpressed in SFTs (ALX4, SHOX2, SIX1) and entire HOX clusters (HOXA, HOXC) were upregulated, as further confirmed by RNAPII profiling of a primary tumor tissue." (PMID 40875449, 2025). "We determined that ALX-4 mRNA level significantly correlated with the tumor grade (P=0.004), stage (p=0.000153), but not gender (P= 0.06)." (PMID 27895854, 2016).
metabolism disorders (1 paper, 2021). "Based on the pseudo-temporal continuum profile, we identified the TF (ALX4, HINFP, CEBPA, CEBPB, DMBX1, MLXIPL, ONECUT1, and RBPJL) and depicted the regulated kernel genes co-networks, which were subjected to the metabolism disorders." (PMID 33462196, 2021).
neurodevelopmental disorder (1 paper, 2020). A behavioral and cognitive disorder with onset during the developmental period that involves impaired or aberrant development of intellectual, motor, or social functions. "Although we have identified that low‐dose TNF‐α can increase the phosphorylation of NF‐κB and the expression of ALX4, a better understanding of immune responses among mice model of neurodevelopmental disorders is likely to discover more potential drugs." (PMID 33304758, 2020).
skeletal dysplasia (1 paper, 2018). Any Mendelian diseases that affects growth and development of the skeleton. "This included seven genes (LIFR, TMEM38B, PLS3, NANS, SLC26A2, ALX4, and PLS3) associated with skeletal dysplasia or bone disease, and four of them were ARE-containing genes with increased expression." (PMID 29727687, 2018).